SLC25A12 (solute carrier family 25 member 12)
Description:
Mitochondrial electrogenic aspartate/glutamate antiporter that favors efflux of aspartate and entry of glutamate and proton within the mitochondria as part of the malate-aspartate shuttle. Also mediates the uptake of L-cysteinesulfinate (3-sulfino-L-alanine) by mitochondria in exchange of L-glutamate and proton. Can also exchange L-cysteinesulfinate with aspartate in their anionic form without any proton translocation. Lacks transport activity towards L-glutamine or gamma-aminobutyric acid (GABA).
Synonyms: Aralar; Aralar1; AGC1; DEE39; EIEE39
Tractability: Antibody: UniProt predicts a signal peptide or a membrane-spanning region. PROTAC: ubiquitination databases record sites on it; its protein half-life has been measured.
Gene: Protein-coding gene on chromosome 2 (171,781,400 to 171,999,859, reverse strand). Ensembl gene ENSG00000115840.
Subcellular location: Mitochondrion inner membrane
Subcellular location (Human Protein Atlas): Nuclear speckles; Cytosol
Pathways (Reactome):
Metabolism: Aspartate and asparagine metabolism; Malate-aspartate shuttle
Protein localization: Mitochondrial protein import
Gene Ontology:
Molecular function: 3-sulfino-L-alanine: proton, glutamate antiporter activity; aspartate:glutamate, proton antiporter activity; calcium ion binding; identical protein binding; protein binding; L-aspartate transmembrane transporter activity; L-glutamate transmembrane transporter activity; acidic amino acid transmembrane transporter activity
Biological process: aspartate transmembrane transport; L-glutamate transmembrane transport; malate-aspartate shuttle; response to calcium ion; L-aspartate transmembrane transport; neutral amino acid transport; proton transmembrane transport; transmembrane transport
Cellular component: mitochondrial inner membrane; mitochondrion; membrane
Genetic constraint (gnomAD): Loss-of-function variants: 24 observed, 64.31 expected, observed/expected ratio (o/e) 0.37, 90% interval 0.27 to 0.52. The upper end of that interval is the gene's LOEUF score, 0.52, which puts it in group 2 of 6, group 1 being the genes least tolerant of losing a copy. Missense variants: 500 observed, 721.7 expected, observed/expected ratio (o/e) 0.69, 90% interval 0.64 to 0.75. Synonymous variants: 241 observed, 256.82 expected, observed/expected ratio (o/e) 0.94, 90% interval 0.84 to 1.04.
Gene-disease validity (ClinGen):
ClinGen rates the evidence that SLC25A12 causes each of these diseases.
mitochondrial disease (autosomal recessive): Moderate.
Homologues: Orthologues: chimpanzee SLC25A12 (99% identical), macaque SLC25A12 (99% identical), dog SLC25A12 (97% identical), pig SLC25A12 (97% identical), rat Slc25a12 (97% identical), guinea pig SLC25A12 (97% identical), mouse Slc25a12 (97% identical), rabbit SLC25A12 (93% identical), tropical clawed frog slc25a12 (84% identical), zebrafish slc25a12 (78% identical), Drosophila melanogaster aralar1 (58% identical), Caenorhabditis elegans K02F3.2 (55% identical). Paralogues in human: SLC25A13 (77% identical), SLC25A24 (17% identical), SLC25A25 (17% identical), SLC25A23 (16% identical), SLC25A22 (15% identical), SLC25A39 (14% identical), UCP2 (14% identical), SLC25A18 (14% identical), SLC25A28 (14% identical), SLC25A29 (14% identical), UCP3 (14% identical), SLC25A48 (14% identical), and 37 more.
Diseases named in the same sentence as SLC25A12 in open-access papers:
SLC25A12 is named in the same sentence as 47 diseases in open-access papers, as found by Europe PMC text mining. Sharing a sentence is not in itself a finding about the gene and the disease. The quoted sentences say what the papers report.
autism (10 papers, 2010 to 2021). Persistent deficits in social interaction and communication and interaction as well as a markedly restricted repertoire of activity and interest as well as repetitive patterns of behavior. "Polymorphisms in the SLC25A12 gene have been shown to strongly associate with autism in candidate gene studies." (PMID 33481009, 2021). "In particular, it has been reported that SLC25A12 is associated with autism of the Han Chinese in Taiwan." (PMID 33716802, 2021). "Polymorphism in SLC25A12 gene, which encodes a mitochondrial aspartate/glutamate carrier, was found to be associated with restricted repetitive behaviors in autism." (PMID 28270747, 2017). "The aim of our study is to specifically test for association between genetic variants in SLC25A12 and AS, to replicate previously shown results and to better understand the molecular genetics of autism." (PMID 24679184, 2014). "For example, the A allele of rs2056206 of SLC25A12 was significantly associated with lower levels of routine and ritual behaviour in autism." (PMID 24679184, 2014). "Several studies have investigated the role of SLC25A12 in the development of autism and SLC25A12 SNPs have been implicated." (PMID 22591576, 2012). "For instance, two independent groups reported overtransmission of the G alleles of two SLC25A12 SNPs in intron 3 (rs2056202) and intron 16 (rs2292813) in autism families." (PMID 21609426, 2011). "SLC25A12 was initially identified as an autism-susceptibility gene through a linkage-directed association study and replication." (PMID 21609426, 2011). "Polymorphism in SLC25A12 gene was found to be associated with autism." (PMID 28270747, 2017). "According to our findings, SLC25A12 may contribute to genetic susceptibility of autism in some populations, but further studies with larger sample size are needed to address and clarify the role of this gene in autism." (PMID 24679184, 2014). "There are also conflicting reports about the association of SLC25A12 with autism." (PMID 23116158, 2012). "We add our findings to this growing body of evidence and suggest that common variation in SLC25A12 auto-regulates expression and may contribute to autism susceptibility." (PMID 22591576, 2012). "SLC25A12 was previously identified by a linkage-directed association analysis in autism." (PMID 21609426, 2011). "Thus, the role of SLC25A12 in increasing autism risk still remains unclear." (PMID 24679184, 2014). "Of note, other SLC family genes, SLC9A9 (MIM 608396), SLC6A4 (MIM 182138), and SLC25A12 (MIM 603667), are causative for autism." (PMID 24297458, 2014). "Previous work has found SLC25A12 to be differentially expressed in autism brains compared to controls." (PMID 22591576, 2012). "Original publications and replication studies have shown that SLC25A12 and EN2 are associated with autism." (PMID 20678243, 2010). "Previous studies have shown that variants in SLC25A12, EN2, ATP2B2 and PITX1, have an association with autism." (PMID 20678243, 2010). "SLC25A12 may play a key role in the pathways that are altered in autism and thus can be considered a candidate gene to test in ASC." (PMID 24679184, 2014). "Taken together, variation in SLC25A12 expression may be involved in the pathophysiology of autism, modifying both neuronal structures and metabolism in the CNS." (PMID 24679184, 2014). "Additionally, the data implicates individual genes SLC25A12, PANX1 and PANX2 as well as pathways previously implicated in autism." (PMID 22591576, 2012). "One such recent study found SLC25A12 expression decreased in autism brains compared to controls." (PMID 22591576, 2012). "Additionally, our results point specifically to SLC25A12 and PANX1/2 and to pathways (such as, methyltransferase, ribosomal components) previously implicated in autism." (PMID 22591576, 2012). "Moreover, targets for the eQTL identified among top signals from autism GWAS include compelling candidate genes such as SLC25A12 and the pannexins." (PMID 22591576, 2012).
autism (continued). "Expression of SLC25A12 may be involved in the pathophysiology of autism because postmortem samples of brain tissue from patients with autism have been found to have stronger expression of SLC25A12 than normal brain samples." (PMID 20678243, 2010). "The expression of DNAJC19, DNM1L, LRPPRC, SLC25A12, SLC25A14, SLC25A24 and TOMM20 were reduced in at least two of the brain regions of autism patients." (PMID 23116158, 2012). "Two of these genes, SLC25A12 and PANX2, were also identified in a recent study of genes differentially expressed in the brains of individuals with autism compared to control brains." (PMID 22591576, 2012). "The expression of DNAJC19, DNM1L, LRPPRC, SLC25A12, SLC25A14, SLC25A24 and TOMM20 were consistently reduced in at least two of the brain regions of autism patients compared to controls." (PMID 23116158, 2012). "However, not all studies have found evidence for association between SLC25A12 and autism." (PMID 21609426, 2011). "We observed a reduced expression of SLC25A12 and SLC25A14 in the ACG and MC of autism patients." (PMID 23116158, 2012). "We demonstrated the association between rs6716901 of SLC25A12 with AS, supporting the role of this gene in the aetiology of ASC, but SLC25A12 might be associated with certain clinical symptoms or behavioural features of autism, rather than the diagnosis of autism itself." (PMID 24679184, 2014).
Epileptic encephalopathy (8 papers, 2018 to 2025). A condition in which epileptiform abnormalities are believed to contribute to the progressive disturbance in cerebral function. "Diseases associated with SLC25A12 protein include epileptic encephalopathy, Asperger Syndrome, delayed cognitive and psychomotor development, psychomotor retardation." (PMID 30537945, 2018). "Pathogenic variants of SLC25A12 result in AGC1 deficiency, which causes infantile epileptic encephalopathy with global psychomotor retardation and brain hypomyelination." (PMID 39858526, 2025). "Variants in the SLC25A12 gene—a glutamate and aspartate exchanger—have been associated with neurodevelopment disorders, including ASD and epileptic encephalopathy." (PMID 40282399, 2025). "SLC25A12 is a severe epileptic encephalopathy with characteristic myelin developmental disorders and a reduced brain N-acetylaspartate content." (PMID 36419532, 2022). "Similar to Slc25a12−/− mice, variants in the human SLC25A12 cause the rare developmental and epileptic encephalopathy 39 (OMIM #612949)." (PMID 35886006, 2022). "Mutations of the gene coding for the brainspecific paralog AGC1 (SLC25A12) lead to early infantile epileptic encephalopathy due to hypomyelination (OMIM 603667)." (PMID 32783608, 2020).
epilepsy (5 papers, 2021 to 2025). A brain disorder characterized by episodes of abnormally increased neuronal discharge resulting in transient episodes of sensory or motor neurological dysfunction, or psychic dysfunction. "Human disease has been linked to biallelic pathogenic variants in MDH1, MDH2, GOT2 and SLC25A12 sharing a clinical overlapping neurological phenotype with epilepsy as dominating feature." (PMID 36079864, 2022). "While variants of SLC25A13 cause CD, variants of SLC25A12 lead to AGC1 deficiency, an infantile‐onset encephalopathy characterized by defective myelin synthesis and associated with hypotonia, arrested psychomotor development, and epilepsy." (PMID 40145619, 2025). "Additionally, some genes (TPRKB, PRAG1, SLC25A12, and TRIM8) have been identified as associated with epilepsy, a neurological disorder characterized by recurrent seizures, that shares similar genetic vulnerability with SZ." (PMID 40282399, 2025). "Mutations in the SLC25A12 gene causing defects in the brain-dominant isoform AGC1 lead to rare neurological disease (OMIM 612949) connected with global cerebral hypomyelination, developmental delay, epilepsy and hypotonia." (PMID 34683364, 2021). "Expression levels of SLC1A1, SLC25A12, ATP2B2 and their related lncRNAs were significantly different between patients with epilepsy and healthy subjects." (PMID 37865723, 2023).
hepatocellular carcinoma (5 papers, 2019 to 2022). A malignant tumor that arises from hepatocytes. "For example, aspartate and glutamate mitochondrial carrier (SLC25A12) overexpression (via unlimited amino acid shuttle) supports aspartate utilization in hepatocellular carcinoma (HCC)." (PMID 35029792, 2021). "More importantly, SLC25A12 expression in hepatocellular carcinoma cell line increased through the modification of histone acetylation." (PMID 33498463, 2021). "For this reason, SLC25A9 and SLC25A12 may become therapeutic targets for hepatocellular carcinoma through fatty acid metabolism." (PMID 36254139, 2022). "SLC25A12 upregulation in hepatocellular carcinoma (HCC) cell lines is essential to promote HCC cell growth." (PMID 32455902, 2020).
autism spectrum disorder (4 papers, 2011 to 2025). A spectrum of developmental disorders that includes autism, and Asperger syndrome. "Several variants in MFHAS1 (rs2271342, rs12677543, rs12682352, rs2409091, rs9644776, rs60315134, rs59046059, rs11784052, rs35039922, rs57312668, rs4841051, rs1039916, rs3789849, rs7820146, rs3925830, rs332037, rs332039, rs332040) and SLC25A12 (rs59844139) were linked to autism spectrum disorder." (PMID 40282399, 2025). "Other mental health problems previously associated with these genes include bulimia nervosa and MDD (NEGR1) autism spectrum disorders (SLC25A12,) and suicide attempts (ADARB1)." (PMID 39971893, 2025).
developmental delay (3 papers, 2017 to 2022). "Mutations in the SLC25A12, which encodes the mitochondrial aspartate-glutamate carrier isoform 1 (AGC1), were identified in patients presenting a developmental delay, hypotonia and intractable seizures associated with a global hypomyelination in the brain." (PMID 28620281, 2017).
Asperger Syndrome (2 papers, 2014 to 2018). "We genotyped three SNPs (rs2056202, rs3765166, and rs6716901) in SLC25A12 in n?=?117 individuals with Asperger syndrome (AS) and n?=?426 controls, all of Caucasian ancestry." (PMID 24679184, 2014).
ovarian carcinoma (2 papers, 2022). A malignant neoplasm originating from the surface ovarian epithelium. "Relatively high mutation rates were also observed in ovarian cancer cell lines for SLC25A13, SLC25A24, SLC25A41, and SLC25A23 and in skin cancer cell lines for SLC25A13, SLC25A8, and SLC25A12." (PMID 36254139, 2022). "In the group of ovarian cancer cells with low SLCO4A1 levels, SLC25A12 coding for the SLC25A12 transporter was identified among the most significant enriched genes." (PMID 36105223, 2022).
acute myeloid leukemia (1 paper, 2022). Acute myeloid leukemia (AML) is a group of neoplasms arising from precursor cells committed to the myeloid cell-line differentiation. "In contrast, the expression of SLC25A4, SLC25A8, SLC25A12, and SLC25A25 was associated with better prognosis of patients in acute myeloid leukemia." (PMID 36254139, 2022).
Alzheimer disease (1 paper, 2025). A progressive, neurodegenerative disease characterized by loss of function and death of nerve cells in several areas of the brain leading to loss of cognitive function such as memory and language. "In T1DM, some of the terms annotated were related to myelin dysregulation (ARHGEF6, CNP, NADK2, PSAP, SLC25A12) and other neurological disorders, such as Alzheimer’s disease (i.e., POA2, APOC1, APOC3, CNP, GSK3B, PON1, PSAP, SELENBP1) or movement disorders." (PMID 39901093, 2025).
bladder urothelial carcinoma (1 paper, 2022). "SLC25A8 and SLC25A12 also had high expression levels in some cancer such as colon adenocarcinoma, bladder urothelial carcinoma, prostate adenocarcinoma, breast invasive cancer, and uterine corpus endometrial carcinoma." (PMID 36254139, 2022).
Brain atrophy (1 paper, 2021). Partial or complete wasting (loss) of brain tissue that was once present. "Mitochondrial aspartate-glutamate carrier isoform 1 (AGC1) deficiency is an ultra-rare genetic disease characterized by global hypomyelination and brain atrophy, caused by mutations in the SLC25A12 gene leading to a reduction in AGC1 activity." (PMID 35095421, 2021).
cervical squamous cell carcinoma (1 paper, 2022). A squamous cell carcinoma arising from the cervical epithelium. "Some genes of SLC25 were associated with poor prognosis of patients in cervical squamous cell carcinoma and endocervical adenocarcinoma, including SLC25A4, SLC25A5, SLC25A8, SLC25A14, SLC25A12, SLC25A23, and SLC25A41." (PMID 36254139, 2022).
glioma (1 paper, 2022). A benign or malignant brain and spinal cord tumor that arises from glial cells (astrocytes, oligodendrocytes, ependymal cells). "Our study showed that LDHA, MRS2, and SLC16A1 were indicators of poor survival, while LDHB and SLC25A12 were indicators of favorable prognosis, suggesting that lactate metabolism is dysregulated in glioma and this dysregulated expression is closely related to tumor progression." (PMID 36698888, 2022). "The results showed that glioma tissues have higher expression of LDHA, HLF1A, SLC16A1, and MRS2 and lower expression of LDHB and SLC25A12 compared with paracancerous tissues." (PMID 36698888, 2022).
Hyperglycemia (1 paper, 2024). An increased concentration of glucose in the blood. "Accordingly, WB analysis reveals a reduction in SLC25A12 in MIC26 KOs compared with WT HepG2 cells in both normoglycemia and hyperglycemia." (PMID 39393820, 2024).
iron-deficiency (1 paper, 2025). "We propose that aspartate accumulates within mitochondria due to iron-deficiency-associated suppressed activity of the proton-dependent mitochondrial aspartate carrier, SLC25A12/13." (PMID 40541943, 2025). "Therefore, it is possible that a reduction in ETC chain activity due to iron deficiency may impair the mitochondrial proton gradient, in turn inhibiting SLC25A12/13 and sequestering aspartate in the mitochondria where it cannot be used for nucleotide synthesis." (PMID 40541943, 2025).
leukodystrophy (1 paper, 2021). Leukodystrophies are a group of rare, progressive, metabolic, genetic diseases that affect the brain, spinal cord and often the peripheral nerves. "More recent MRI support for the classification of SLC25A12-related disease as leukodystrophy, but this is still debated." (PMID 35095421, 2021).
Leukoencephalopathy (1 paper, 2024). This term describes abnormality of the white matter of the cerebrum resulting from damage to the myelin sheaths of nerve cells. "Another entity belonging to mitochondrial diseases for which efficient treatment with a ketogenic diet was shown is leukoencephalopathy conditioned by SLC25A12 molecular variants." (PMID 38542723, 2024).
mental disorder (1 paper, 2025). A disease that has its basis in the disruption of mental process. "Furthermore, some of these genes (e.g., NEGR1, PTBP2, BCL11A, ARNTL, SLC25A12, ADARB1) were identified in a recent study investigating the genetic overlap between AN and mental disorders, further supporting their relevance to AN." (PMID 39971893, 2025).
myopia (1 paper, 2023). "Interestingly, our lead AL-associated SNP (rs57718990) at SLC25A12 has been previously reported to be associated with myopia age-of-onset." (PMID 37351342, 2023).